RN7SKP237 (RN7SK pseudogene 237)
Gene: Miscellaneous RNA gene on chromosome 4 (139,685,127 to 139,685,427, reverse strand). Ensembl gene ENSG00000201533.
Homologues: Orthologues: chimpanzee 7SK (95% identical). Paralogues in human: RN7SKP255 (78% identical), RN7SKP9 (78% identical), RN7SKP71 (77% identical), RN7SKP28 (76% identical), RN7SKP50 (76% identical), 7SK (76% identical), RN7SKP176 (76% identical), RN7SKP243 (76% identical), RN7SKP146 (75% identical), RN7SKP15 (75% identical), RN7SKP203 (75% identical), RN7SKP37 (75% identical), and 283 more.